RIPK2 (receptor interacting serine/threonine kinase 2)
Diseases named in the same sentence as RIPK2 in open-access papers (continued):
Sharing a sentence is not in itself a finding about the gene and the disease.
infection (44 papers, 2012 to 2024). The state of being infected such as from the introduction of a foreign agent such as serum, vaccine, antigenic substance or organism. "Infection at multiplicity of 0.1 caused a 2.5-fold increase in RIPK2 expression (lanes 1&3) and further increase was observed in infected MDP-treated cells (lanes 3&4)." (PMID 26830977, 2016). "The infection of Shigella induced the K63‐linked ubiquitination of RIPK2 (Fig EV1D)." (PMID 36221902, 2022). "Among the infection-specific ISGs upregulated during ΔHA-Cre infection are genes associated with apoptosis (Ripk2, Casp1, Ifi27, Pmaip1) and E3 ubiquitin ligases and proteasome genes, some of which are known to be involved in MHC-I antigen processing (Neurl3, Rnf19b, Psmb9)." (PMID 32790753, 2020). "Thus, the underlying infection determines the impact of RIPK2 and CYLD on the outcome of the disease and our identification of a direct inhibition of RIPK2 by CYLD provides a mechanistical explanation of the antagonistic effects of these two signaling molecules." (PMID 26834734, 2015). "The results revealed that the expression of RIPK2 increased at 12 h after infection in a time-dependent manner." (PMID 39696641, 2024). "Among those GO terms, at the acute infection stage, some targeted DEmRNAs (e.g., Ccl2, Lgals3, H2-DMb2, Ripk2, and Ndfip1) were enriched in the “regulation of T cell activation” term (GO:0050863)." (PMID 38229193, 2024). "In HeLa cells, RIPK2 forms high-molecular-weight complexes, also known as RIPososmes, upon infection with invasive bacterial pathogens: i.e., Shigella flexneri and enteropathogenic E. coli (EPEC)." (PMID 37306596, 2023). "Violin plots demonstrate that Nod1, Nod2 or Ripk2 were expressed by very few ME cells of any category, prior to NTHi infection." (PMID 35903351, 2022). "In various fish, myd88 has been detected to have high transcripts levels after pathogens infection, while little is known for fish tradd, ripk-2 and act1 genes." (PMID 33732247, 2021). "Formation of RIPK2 complexes not only was not limited to Shigella but also seen upon infection with enteropathogenic E. coli (EPEC E2348/69)." (PMID 31350258, 2019). "A priori upregulation of both NOD1 and RIPK2 in MAP-infected macrophages would suggest an efficient host control over the intracellular infection." (PMID 31969876, 2019). "Accordingly, RIPK2 S176A induced more, and RIPK2 S176E less, IL-8 mRNA expression at early time points of infection, compared to wt RIPK2." (PMID 31350258, 2019). "Endogenous RIPK2 decreased in the soluble fraction upon infection, whereas it accumulated in the pellet fraction." (PMID 31350258, 2019). "Here, we demonstrate that RIPK2 forms detergent insoluble complexes in the cytosol of host cells upon infection with invasive enteropathogenic bacteria." (PMID 31350258, 2019). "Immunoblot analysis confirmed upshift of RIPK2 starting 2 h p.i. in cells treated with a control siRNA and infection independent upshift in cells with reduced XIAP levels." (PMID 31350258, 2019). "Evaluation of the subcellular localization of RIPK2 during infection showed that EGFP-RIPK2 localized to F-actin–rich bacterial entry sites at early times of infection (30 min to 1 h p.i.)." (PMID 31350258, 2019). "We found RIPK2 to form high molecular weight complexes (RIPosomes) in the cytosol of epithelial cells upon infection with invasive bacterial pathogens such as Shigella flexneri and enteropathogenic Escherichia coli." (PMID 31350258, 2019). "RIPK2 complex formation was accompanied by appearance of higher molecular weight signals for both inhibitors at later time points of infection." (PMID 31350258, 2019). "Although total RIPK2 levels slightly decreased with infection, an increase of the ratio of the RIPK2 pellet/total fraction at later time points of infection was evident, showing that the HeLa EGFP-RIPK2 line reflects the properties of the endogenous protein." (PMID 31350258, 2019).
infection (continued). "S176E showed RIPosome formation similar to WT RIPK2 protein, whereas RIPK2 S176A led to RIPosome formation and upshift earlier upon infection, as compared with wt." (PMID 31350258, 2019). "The appearance of these structures upon infection followed the same kinetic as the change in the electrophoresis migration behavior of RIPK2." (PMID 31350258, 2019). "iSCs also sensed infection with live Salmonella typhimurium, rapidly expressing IL-1 family cytokines via a RIPK2/p38MAPK-dependent signaling process." (PMID 24137162, 2013). "Moreover, we found that pathogens infection significantly increased the expression of RIPK2, especially mycobacterium tuberculosis which were prone to immune escape (log FC = 3.4, p < 0.001)." (PMID 35508972, 2022). "Furthermore, we examined NOD1 and RIPK2 expression at different infection time points in cultured U251 cells and observed that JEV infection upregulated their expression in a time-dependent manner, as determined by qRT-PCR and immunoblot analysis." (PMID 35638852, 2022). "While we cannot rule out that PR released during virus entry might target RIPK1 and RIPK2, our data suggest that RIPK1 and RIPK2 cleavage occurs at later stages of infection and depends on transcription of viral genes." (PMID 26297639, 2015). "Interestingly, pathogen infection also significantly increased the expression of RIPK2, suggesting that RIPK2 may be a universal regulatory factor for immune escape of tumor and pathogen." (PMID 35508972, 2022). "Receptor interacting serine/threonine kinase 2 (RIP2), ubiquitous in many tissue/cell types, is the key regulator of immune and inflammatory responses for many diseases, including avian pathogenic E. coli (APEC), which causes a wide variety of localized or systemic infections." (PMID 35501708, 2022). "Consistent with this, iSCs internalize and respond rapidly to in vitro infection with the flagellated bacterium Salmonella typhimurium, increasing their expression of IL-1β and IL-33 at both the mRNA and protein level, with this sensing dependent on RIPK2/p38MAPK signaling." (PMID 24137162, 2013). "The Western blotting results showed that TRIF, MAVS, and STING were most effective in inhibition, while MyD88, RIPK2, ASC, and CARD9-BCL10-MALT1 (CBM) were less effective in inhibiting N protein expression at 72 h post-infection." (PMID 37631972, 2023). "The expression of C6, C7, IRAK4, LBP, and RIPK2 was significantly upregulated after infection with A. hydrophila, while the expression of SIPA1L2 and NFATC1 was significantly downregulated after infection." (PMID 36910190, 2023). "NOD2 and RIPK2 were required for about half of the IFN-α and IFN-β transcription and secretion within 4 hours of infection with Mtb." (PMID 37262021, 2023). "The Western blotting results show that TRIF and MAVS are most effective in inhibition, MyD88, RIPK2, CBM and STING are intermediate in inhibition, and ASC is barely effective in inhibition of N protein expression at 48 h and 72 h post infection of PRRSV." (PMID 34696285, 2021). "The RIPK2-mediated signaling pathway leads to the activation of NF-κB and MAP kinases that induce autophagy following infection." (PMID 31164887, 2019). "As a result, they demonstrated the induction of pro-apoptotic genes, such as RIPK2, BID, and tBID after infection." (PMID 26803467, 2016). "PR-mediated proteolytic modification of RIPK1 and RIPK2 therefore likely represents an important strategy of HIV-1 to counter cellular restriction and modulate the host response to infection." (PMID 26297639, 2015). "The induction of pro-apoptotic genes, such as RIPK2, BID and tBID was seen after infection with all three isolates, however apoptotic pathways were affected to a lesser degree by Mah 1655 than by Maa 1794 and Mah VI101." (PMID 24450835, 2014). "Noteworthy, in our studies we observed the return of full-length RIPK1, RIPK2 and PARP protein levels at later time points (24 h) following infection." (PMID 22685397, 2012).
infection (continued). "This study revealed that the expression of NOD1 and RIPK2 is upregulated in BV2 cells and mouse brain tissues during PRV infection, which may be influenced by other signalling pathways after infection, and further research is needed." (PMID 39696641, 2024). "These variants were found in inflammasome genes (NLRP1/3 and CASP1), genes mediating inflammasome inactivation via auto- and mitophagy (RIPK2 and MEFV), and genes involved in the response to infection with DNA viruses (POLR3A, DHX58, and IFIH1) and type-1 interferons (TYK2 and PTPRC)." (PMID 37626706, 2023). "During infection with avirulent Mtb (H37Ra), inclusion of a dominant negative RIPK2 construct in THP-1 cells did not significantly alter apoptosis, despite the fact that MDP was capable of suppressing apoptosis in the same uninfected cells." (PMID 37262021, 2023). "These variants were found in inflammasome genes (NLRP1/3, CASP1), genes mediating inflammasome inactivation via auto and mitophagy (RIPK2, MEFV), and genes involved in response to infection with DNA viruses (POLR3A, DHX58, IFIH1) and to type-1 interferons (TYK2, PTPRC)." (PMID 31235738, 2019). "As expected, NOD1 knockdown reduced IL-8 secretion upon infection but did not affect IL-8 secretion induced by autoactivation due to overexpression of RIPK2, compared with control siRNA-treated cells." (PMID 31350258, 2019). "This suggests that the regulation of RIPK2 ubiquitination by CYLD (and LUBAC and OTULIN) could influence the response to infection by intracellular bacteria." (PMID 26997266, 2016). "First, RIPK2 activates NF-κB signaling and mitogen activated protein (MAP) kinases upon infection." (PMID 27482714, 2016). "In sharp contrast, RIPK2 promotes inflammation and lethality during infection with the Gram-negative bacteria Pseudomonas aeruginosa and E. coli due to excessive activation of NF-κB and MAPK." (PMID 26834734, 2015). "Notably, we observed that XIAP levels were reduced upon infection in cells expressing RIPK2, RIPK2 S176A, and RIPK2 S176E but not in cells expressing RIPK2 Y747F and correlated with the induction of RIPosome formation." (PMID 31350258, 2019). "Albeit overexpression of RIPK2 led to some NF-κB activation and induction of IL-8, the inflammatory response 6 h post infection (p.i.)was much higher, also in cells induced for EGFP-RIPK2 expression for 16 h, compared with noninduced cells." (PMID 31350258, 2019). "We also found that deletion of signaling molecules that act upstream of type I IFN production including multiple TLRs, RIPK2, cGAS/STING, or MAVS pathways, did not increase BMDM fusion during infection while control BMDMs lacking MyD88 and TRIF or IFNAR1 extensively fused." (PMID 32150572, 2020). "Inhibition of RIPK2 with the tyrosine kinase inhibitor gefitinib and the RIPK2-specific compound GSK583 also led to spontaneous induction of RIPosomes independent of infection." (PMID 31350258, 2019).
tumor (44 papers, 2018 to 2026). "The loss of RASSF1A is considered a potential risk factor for IBC, with active RIPK2 possibly playing a role in the cellular response and promoting tumor progression." (PMID 40406369, 2025). "Our findings demonstrate a significant association between RIPK2 and the degree of immune cell infiltration within certain tumor microenvironments." (PMID 38164277, 2024). "TCGA data were utilized to examine the association between RIPK2 expression and various factors including tumor immune infiltration and immune-related biomarkers." (PMID 38164277, 2024). "We also explored the correlation between mutations in RIPK2 and clinical outcomes in patients with different tumours." (PMID 35473583, 2022). "We used the TCGA, CPTAC, HPA databases to analyse the expression, mutation, and prognosis of RIPK2 in human tumours." (PMID 35473583, 2022). "The present study also investigated the expression status of genetic variation of RIPK2 in various tumours, including gene amplification, gene mutation and gene deletion." (PMID 35473583, 2022). "We investigated the somatic mutations, copy number variation, expression profiling, immunological features of the tumor microenvironment, and clinical association significance of the RIPK2 gene in this work." (PMID 33790054, 2021). "In addition, Amplification was the main type of RIPK2 in tumour mutation state, and the amplification rate was about 8.5%." (PMID 35473583, 2022). "Our analyses revealed that the occurrence and development mechanisms of RIPK2 in human tumours were mainly associated with NOD-like signalling pathways, the NF-kappa B signalling pathway, I-kappa B kinase/NF-kappa B signalling, ribonucleoprotein granule and ubiquitin-like protein ligase binding." (PMID 35473583, 2022). "Survival outcome was associated with tumor stage and RIPK2 expression." (PMID 34356990, 2021). "So we next evaluated the correlation of the RIPK2 over-expression and the mutation profile of these genes to examine whether the tumor samples with RIPK2 upregulation were enriched for some specific somatic alterations." (PMID 33790054, 2021). "The loss of RASSF1A is seen as a potential risk factor in IBC, with RIPK2 playing a regulatory role in tumor progression, Further studies show RIPK2’s involvement in metastasis and tumor growth, suggesting it could be a valuable prognostic marker and therapeutic target in IBC." (PMID 40406369, 2025). "However, it remains unclear whether a common molecular mechanism underlies the role of RIPK2 in the occurrence and development of different tumours." (PMID 35473583, 2022). "Xenograft tumor experiments confirmed that inhibition of RIPK2 or P-gp enhanced the efficacy of DTX in suppressing PC-3/DTX growth." (PMID 41563982, 2026). "Increased levels of RIPK2 are linked to unfavorable outcomes in TNBC and facilitate tumor advancement through the activation of the NF-κB and JNK pathways." (PMID 41017855, 2025). "Restoring miR-146a or pharmacologically inhibiting its targets (TRAF6, RIPK2) reverses these pathological changes and prevents tumor development." (PMID 41463227, 2025). "Single-cell RNA sequencing and spatial transcriptomics revealed that a tumor cell cluster with high RIPK2 expression exhibited enhanced metastatic potential, closely linked to bacterial invasion." (PMID 40185717, 2025). "The upregulation of RIPK2 and NF-κB further supports the involvement of innate immune signaling and inflammatory cascades in sustaining tumor progression and immune evasion." (PMID 41304988, 2025). "Based on the findings of our in vivo experiment, we have successfully illustrated that the suppression of RIPK2 effectively impedes the proliferation of tumor cells in vivo through its influence on the cell cycle-associated protein PCNA and apoptosis." (PMID 38164277, 2024). "In this study, we conducted a comprehensive analysis of RIPK2 expression within the tumor microenvironment, utilizing the immune score and stromal score as indicators." (PMID 38164277, 2024).
tumor (continued). "Lastly, the impact of targeting RIPK2 on the growth of GC cells was confirmed through tumor formation assay, immunohistochemistry, and Tunnel assays." (PMID 38164277, 2024). "After understanding the tumor-promoting role of RIPK2 in PC, we next explored the potential action mechanisms involved." (PMID 37016317, 2023). "Herein, we would like to evaluate the feasibility of RIPK2 being the anti-tumor drug target and summarize the research progress of RIPK2 inhibitors." (PMID 37324457, 2023). "Mechanistically, RIPK2 directly contributes to the tumor’s multiplication, invasion, and metastasis by promoting NF-κB and JNK activation." (PMID 37324457, 2023). "The special tumor microenvironment of PC is one of the key factors for its refractory feature and drug resistance, so the PC inhibition by RIPK2 mediated tumor microenvironment remodeling is intriguing to be explored." (PMID 37016317, 2023). "As a whole, in tumor types with high RIPK2 expression, RIPK2 can indeed effectively promote the malignant progression of the tumor, which has an undesirable effect on prognosis." (PMID 37324457, 2023). "Apart from the alteration of the tumor microenvironment, regulatory networks have also been discovered between RIPK2 and tumor driver genes." (PMID 37324457, 2023). "In this review, we will give an overview of the integrated role of RIPK2 in the progression of tumor malignancy and the feasibility of RIPK2 as an anti-tumor therapeutic target." (PMID 37324457, 2023). "As for anti-tumor therapy, we deem that the application of RIPK2 kinase inhibitors is superior to RIPK2 PROTACs." (PMID 37324457, 2023). "Consistent with the in vitro cell proliferation results, RIPK2-KO 22Rv1 xenografts had a significant but modest reduction in tumor growth rate, weight, and size, compared with control tumors." (PMID 35115556, 2022). "RIPK2 not only plays an important role in inflammatory and immune diseases, but also participates in tumour invasion and metastasis." (PMID 35473583, 2022). "From the TCGA database, we determined the expression status of genetic variation of RIPK2 in different tumours." (PMID 35473583, 2022). "As expected, the frequency of RIPK2 mRNA overexpression also increases with PC progression, rising from 0.8% in tumor-adjacent normal tissue to 45.4% in metastatic or castration-resistant PC." (PMID 35115556, 2022). "Consistent with our result, RIPK2 was reported to affect tumor progression by promoting cellular autophagy and to accurately predict prognosis in PRAD." (PMID 35508972, 2022). "To summarize, this is the first study to comprehensively analyse the correlation between RIPK2 expression and clinical prognosis, genetic variation, immune cell infiltration and the molecular mechanism of tumours." (PMID 35473583, 2022). "In the BRCA mouse model, RIPK2 knockout increases the chemotherapy sensitivity of docetaxel, inhibits tumour volume and reduces lung metastasis." (PMID 35473583, 2022). "Our pancancer study provided a relatively comprehensive description of the carcinogenic effects of RIPK2 in different tumours, and provided useful information for further study of RIPK2." (PMID 35473583, 2022). "We analyzed the relationship between the expression of RIPK2 and the drug response in 60 tumor cell lines." (PMID 35508972, 2022). "To further understand the occurrence and development mechanism of RIPK2 in tumours, we screened RIPK2-binding proteins and genes related to RIPK2 expression." (PMID 35473583, 2022). "We next evaluated the total protein expression of RIPK2 in tumour tissues and normal tissues in BRCA, LUAD, COAD, UCEC, OV and KIRC in the CPTAC database." (PMID 35473583, 2022). "Knocking down RIPK2 reduces the activity of breast cancer cells, and increases sensitivity to docetaxel, reducing lung metastasis and tumor mass in a xenograft mouse model." (PMID 35508972, 2022).